SLC6A4 (solute carrier family 6 member 4)
Diseases named in the same sentence as SLC6A4 in open-access papers (continued):
Sharing a sentence is not in itself a finding about the gene and the disease.
Anxiety (continued). "The Slc6a4 KO mice have increased anxiety, increased stress, decreased aggression, increased acoustic startle, decreased exploratory behavior, and decreased motor agility." (PMID 29651330, 2018). "Slc6a4 KO mice display increased anxiety-like behaviors, reduced aggression, and exaggerated stress responses." (PMID 29651330, 2018). "Our results revealed that the expression levels of the 5-HT-related synthesizing enzyme (tph2) and transporter (slc6a4) genes were significantly depleted in parallel to the occurrence of anxiety-like behaviors in LPS-induced offspring." (PMID 28650979, 2017). "We concluded that maternal immune activation induced by exposure to a low dose of LPS decreased cerebral 5-HT levels in parallel to the down-regulation of the tph2 and slc6a4 genes and in conjunction with anxiety-like behaviors in offspring." (PMID 28650979, 2017). "Our results indicated that the concentration of the cerebral 5-HT and gene expression of the tph2 and slc6a4 were decreased in conjunction with the appearance of anxiety-like behaviors in the adolescent and adult offspring of the LPS-induced groups." (PMID 28650979, 2017). "The purpose of this study is to determine the relationship between personality, the presence of the polymorphism in the 5HTT (SLC 6A4) promoter region and the severity of anxiety and depressive symptoms in a homogenous group of elite athletes." (PMID 27257942, 2016). "Among all these genes, the SLC6A4 (5-HTT) is one of the most widely investigated genes in relation to anxiety-related personality traits." (PMID 23781201, 2013). "In addition, we explored the association between SLC6A4 and TPH2 methylation and measures of early life and recent stress, depressive and anxiety symptoms on 297 healthy individuals." (PMID 38802956, 2024). "Interestingly, ACK also promoted an increase in Slc6a4 mRNA levels and increased juvenile anxiety behavior." (PMID 38398814, 2024). "Moreover, the spatial distributions of MAOA, MAOB, COMT, and SLC6A4 on the left side of the network suggested that these genes significantly contributed to the pathogenesis of anxiety." (PMID 38684743, 2024). "Medications that block this transporter by itself, or in conjunction with blocking SLC6A4 (Solute Carrier Family 6 Member 4, the serotonin transporter), another one of our findings, also increased in expression in high anxiety, have been shown to be useful clinically in anxiety disorders." (PMID 36878964, 2023). "In addition, a study in marmosets linked a SERT gene (SLC6A4) promotor haplotype associated with low SERT expression and an anxiety‐prone phenotype to reduced brain 5‐HT2AR binding." (PMID 32697408, 2020). "Functional assessment of c-Fos after associated foot shock, electrophysiological recordings of GABAergic synaptic transmission, differential expression of the Slc6a4 gene in serotonergic neurons were combined with locomotor and anxiety-like measurements in different contextual settings." (PMID 28972592, 2017). "The results of the study described in this article did not demonstrate any influence of the 5-HTTLPR (SLC6A4) polymorphism on the mood and the level of anxiety of menopausal women." (PMID 25547397, 2014). "Basic descriptive statistics concerning anxiety as a state according to STAI X-1 and anxiety as a trait, according to STAI X-2 of the 44-bp polymorphism in the 5-HTTLPR (SLC6A4) promoter region and of the 30-bp VNTR polymorphism in the MAO A promoter region among women in the study." (PMID 25547397, 2014). "Elevated SLC6A4 methylation is also associated with generalized anxiety disorder (GAD) and panic disorder, correlates with increased anxiety traits, social anxiety, and amygdala hyperreactivity, and may explain how altered serotonin signaling affects fear processing and threat detection." (PMID 41234420, 2025).
Anxiety (continued). "Thus, in the present study, we investigated the effects of a HFD treatment for 9 weeks on the gut microbiome, expression of tph2, htr1a and slc6a4 genes in the brainstem raphe nuclei, and anxiety-related defensive behavioral responses in adult male Wistar rats." (PMID 38705984, 2024). "Disfunctions of this area in subjects with the s/s genotype of the SLC6A4 promoter region of the serotonin transporter (5-HTT) have been considered as an “overactive metabolic state”, possibly related to an increased susceptibility for developing an anxiety-depression spectrum disorder." (PMID 39051251, 2024). "Elevated adenine levels resulting from ATP depletion due to alcohol consumption led to emotional symptoms such as lethargy and anxiety, accompanied by altered expression of P2X4, P2X7, and SLC6A4 genes." (PMID 38491208, 2024). "Other studies demonstrated a correlation between methylation and reduced levels of SLC6A4 mRNA and an association between methylation levels in multiple CpG sites in the SLC6A4 promoter region with depressive symptoms, HPA axis reactivity, amygdala activation patterns, anxiety, and burnout." (PMID 41301846, 2025). "SLC6A4, SLC6A2, and DRD2 are known to be involved in the serotonergic and dopaminergic systems, which impact the perception of exercise-induced fatigue and anxiety." (PMID 39200631, 2024). "To conclude, our findings do not support an association between SLC6A4 or TPH2 methylation and 5-HTT or 5-HT4 brain levels or measures of early life stress, anxiety or depressive symptoms." (PMID 38802956, 2024). "The analysis did not demonstrate a clear relationship between mood and anxiety level and the presence of the 5-HTTLPR (SLC6A4) polymorphism and the 30-bp VNTR polymorphism in the MAO A promoter region." (PMID 25547397, 2014). "The SLC6A4 gene is not involved in anxiety-related traits measured by TCI and NEO in psychiatrically healthy subjects." (PMID 21453464, 2011). "Finally, immunization with M. vaccae prevented stress-induced increases in expression of serotonergic genes, including Tph2 and Slc6a4, in the DRD, a subregion of the dorsal raphe nucleus that has been well-characterized as responsive to stress- and anxiety-provoking stimuli." (PMID 33469429, 2020). "Correlation analysis revealed a strong negative relationship between Slc6a4 levels and latency to enter the light zone (r = –0.90, p < 0.001), indicating that animals with lower serotonergic transporter expression displayed higher anxiety and behavioral inhibition." (PMID 41415278, 2025). "More studies are needed to rule out a role of SLC6A4 and TPH2 methylation as biomarkers for environmental stress, depressive or anxiety symptoms." (PMID 38802956, 2024). "An interesting study compared changes in SLC6A4 methylation after Cognitive Behavior Treatment (CBT) in anxious children, considering those that remitted as compared to those that did not remit from their primary anxiety diagnoses." (PMID 30218003, 2018). "In addition, variation in the 5-HTT gene SLC6A4 may modulate attention to threat, anxiety, negative affect and fear." (PMID 26473596, 2015). "Moreover, variation in the 5-HTT gene SLC6A4, indicating decreased transcription, may modulate anxiety and negative affect." (PMID 26473596, 2015).
Obesity (47 papers, 2011 to 2025). Accumulation of substantial excess body fat. "Increased methylation of the SLC6A4 promotor region is shown to be linked to the development of obesity in human subjects." (PMID 37899888, 2023). "SLC6A4 promoter hypermethylation is significantly associated with an increased prevalence of obesity." (PMID 36678277, 2023). "Associations between methylation at SLC6A4 with cardiometabolic markers implies potential functional relevance of methylation at these sites in contributing to obesity and other cardiovascular or metabolic diseases." (PMID 34354616, 2021). "Polymorphisms within SLC6A4 have been associated with obesity in children and adults, while differential methylation of the promoter region of SLC6A4 in peripheral blood has been associated with concurrent obesity in adults." (PMID 30622309, 2019). "In agreement with this, we showed that differential methylation of SLC6A4 in adipose tissue from a separate population was also associated with obesity." (PMID 30622309, 2019). "The human brain and placenta express SLC6A4, which encodes the serotonin transporter that plays a key role in regulating the serotonin system; a growing body of evidence has shown its association with obesity and metabolic diseases." (PMID 36431006, 2022). "However, in an adult twin study, higher SLC6A4 promoter methylation in peripheral blood leukocytes was associated with obesity." (PMID 36431006, 2022). "Methylation at SLC6A4 also has been related to cardiometabolic health, as one study found promoter hypermethylation in blood leukocytes to be significantly associated with an increased prevalence of obesity." (PMID 34354616, 2021). "Also, several studies investigated genetic association of serotonin transporter gene (SLC6A4), 5-HTTLPR polymorphism, with Type 2 Diabetes Mellitus (T2DM) 6,17–19 and the relation between the SLC6A4 alleles with obesity 20,21." (PMID 31379997, 2019). "Although beyond the scope of this study, additional experiments involving whole genome methylation profiling, or assessment of methylation of genes such as PPARGC1A, IGFBP-1, and SLC6A4, which have previously been shown to be associated with T2D and obesity, may be beneficial." (PMID 34485290, 2021). "The methylation analysis of this gene showed that people with obesity had lower methylation of SLC6A4 CpG5 and lower expression of SLC6A4 mRNA in adipose tissue compared to people with a normal BMI." (PMID 38666884, 2024). "In this scenario, in vivo study demonstrated that transgenic mice overexpressing SLC6A4 are lighter and shorter than controls; on the other hand, Slc6a4 knockout mice develop late-onset obesity, hepatic steatosis, glucose intolerance, and insulin resistance." (PMID 36678277, 2023). "Meanwhile, knockout of the SLC6A4 gene appears to result in the development of obesity, fatty liver disease, and insulin resistance." (PMID 37899888, 2023). "Comparison of SLC6A4 methylation across tissue types within the same individual would permit a greater understanding of tissue-specific differences in DNA methylation and the utility of SLC6A4 as a marker of future obesity." (PMID 30622309, 2019). "Functional gene SLC6A4 (ENSP00000270349) has also been predicted to be a correlated gene of obesity and psychiatric disease." (PMID 29258237, 2017). "Our group also reported associations between global DNA methylation and insulin resistance, and between serotonin transporter gene (SLC6A4) promoter methylation and obesity measures in this same monozygotic twin sample." (PMID 23116433, 2012). "Moreover, in obese adults lower SLC6A4 methylation in adipose tissue was accompanied by a change in SLC6A4 mRNA expression, suggesting that altered SLC6A4 methylation may be of functional relevance in obesity." (PMID 30622309, 2019). "The common targets of obesity, T2DM, and NAFLD are solute carrier family 6 member 4 (SLC6A4), acetylcholinesterase (ACHE), opioid receptor Mu 1 (OPRM1), and glycogen synthase kinase 3 beta (GSK3B)." (PMID 39575382, 2024).
Obesity (continued). "The purpose of this study was to test whether mice lacking SERT gene Slc6a4 function (SERT−/−) exhibit reduced food intake, thereby protecting them against obesity and diabetes." (PMID 22412882, 2012).
autism (46 papers, 2005 to 2025). Persistent deficits in social interaction and communication and interaction as well as a markedly restricted repertoire of activity and interest as well as repetitive patterns of behavior. "SLC6A2 and SLC6A4 are associated not only with gastrointestinal disease, but also with anorexia nervosa, acute anxiety, and autism." (PMID 29861771, 2018). "Linkage and association analysis at the serotonin transporter (SLC6A4) locus in a rigid-compulsive subset of autism." (PMID 21034472, 2010). "ITGB3 has been reported to show genetic and expression interaction with SLC6A4, leading to increase of autism susceptibility." (PMID 19949574, 2009). "Positron emission tomography (PET) imaging studies have demonstrated abnormal 5‐HT synthesis in brain regions in autism and a polymorphism in the gene for the serotonin transporter (SLC6A4) has been associated with increased cerebral cortex grey matter volume in children with ASD." (PMID 31325179, 2019). "SLC6A4 is a second candidate gene with a repeatedly reported causal link to autism." (PMID 19949574, 2009). "Of note, other SLC family genes, SLC9A9 (MIM 608396), SLC6A4 (MIM 182138), and SLC25A12 (MIM 603667), are causative for autism." (PMID 24297458, 2014). "First, although the transcription of SLC6A4 is normal in subjects with autism, the level of SERT protein at the pre-synaptic membrane is decreased because of an impairment of the trafficking system." (PMID 24834316, 2014). "Our results show that, at least, SLC6A4 mRNA expression is normal in the raphe region of post-mortem brains from subjects with autism." (PMID 24834316, 2014). "The more proximal peak at ~53 cM lies in close proximity (~150 kb) to the serotonin transporter (SLC6A4) locus, long considered to be an attractive functional candidate gene for autism and other neuropsychiatric conditions." (PMID 15647115, 2005). "An IMGSAC follow-up screen for autism reported a maximum multipoint LOD score of 2.34 at HTTINT2 in the SLC6A4 gene on chromosome 17q11.2." (PMID 15647115, 2005). "A work in autism showed that the reduction in social interactions caused by partial Fmr1 protein deficiency occurs in a mixed FVB/N-129/OlaHsd background in a similar manner then in partial serotonin transporter (Slc6a4-/y) deficient mice and not in C57BL/6J animals." (PMID 34473777, 2021). "While that study includes the male animals from the Slc6a4 KO and Slc6a4 Ala56 KI models, that paper did not examine the individual models in detail but only the similarities and differences across multiple autism-related mouse models." (PMID 29651330, 2018). "Although changes in SERT function and expression have been implicated in autism, mRNA expression of the SLC6A4 gene that encodes SERT in the brains of autistic individuals has never been reported." (PMID 24834316, 2014). "In addition, a study of post-mortem brains revealed that the SLC6A4 expression level was not affected in subjects with autism, but the NSF expression level in the raphe region tended to be decreased; however, this potential trend is not statistically significant." (PMID 24834316, 2014). "Alterations in the mRNA expression of SERT (SLC6A4) and the SERT-binding protein in the post-mortem brains and the lymphocytes of autism patients were compared to nonclinical controls." (PMID 24834316, 2014).
mood disorder (45 papers, 2012 to 2026). A cognitive disorder a disturbance in which the person's mood is hypothesized to be the main underlying feature. "SLC6A4 polymorphisms have been extensively examined in mood disorders and antidepressant treatment, while little work has been performed in relation to antipsychotic response, with few significant results." (PMID 31040787, 2019). "As VNTRs in SLC6A4 gene are related to the mood disorders, suicide risk and smoking-related personality traits, we wanted to address the association between SLC6A4 and nicotine dependence." (PMID 30559666, 2018). "Another gene that is widely influenced by early-life experiences and implicated in mood disorders is the serotonin transporter gene (5HTT or SLC6A4)." (PMID 25904853, 2015). "Interestingly, the serotonin system and the SLC6A4 gene have been implicated in the pathophysiology of psychiatric disorders which show a strong comorbidity with tobacco use disorder, including mood disorders and alcohol abuse." (PMID 24968820, 2014). "Specifically, genes, such as NR3C1, SLC6A4, BDNF, FKBP5, SKA2, and OXTR, exhibit alterations in DNA methylation patterns that are frequently linked to mood disorders." (PMID 38792892, 2024). "The role of serotonin in the etiopathogenesis of mood disorders has been documented, and the SLC6A4 gene encoding for the serotonin transporter (5-HTT) is among the most frequently investigated genes in depressive symptoms." (PMID 25547397, 2014). "Indeed, most previous studies linking peripheral SLC6A4 or TPH2 methylation to stress-related phenotypes were based on patients with mood disorders or individuals who were exposed to intense environmental stress." (PMID 38802956, 2024).
anxiety disorder (37 papers, 2008 to 2025). A category of psychiatric disorders which are characterized by anxious feelings or fear often accompanied by physical symptoms associated with anxiety. "SLC6A4 promoter regions have functional polymorphism, which has been associated with manifold aspects of neuroticism and psychopathology, particularly anxiety disorder traits." (PMID 39410900, 2025). "Genetic variations in SLC6A4 have been associated with altered responses to SSRIs and susceptibility to anxiety disorders." (PMID 38684743, 2024). "This correlates with total SLC6A4 expression and has been associated with an increased risk for anxiety disorders and suicidal behaviour." (PMID 32560344, 2020). "Numerous studies have suggested the relationship between SLC6A4 polymorphisms and some mental disorders, including depressive and anxiety disorders." (PMID 28951738, 2017). "Especially, a polymorphism within the promoter region of the serotonin transporter (5-HTT) gene (SLC6A4, 5HTT) located on chromosome 17q11.1-q12 has been shown to play an important role in trait anxiety and anxiety disorders." (PMID 23630477, 2013). "APA of SLC6A4 plays a role in several neurological conditions and interestingly treatment of mice with the SLC6A4-selective antidepressant/anxiolytic drug fluoxetine, which has been shown to reduce anxiety disorders, increases expression of the distal polyadenylation form of SLC6A4." (PMID 32560344, 2020). "These actions were shown to modulate crucial target proteins, including SLC6A4, COMT, and MAOA, thereby exhibiting a significant therapeutic impact on anxiety disorders." (PMID 38684743, 2024).